KIF3C (kinesin family member 3C)
Description:
Microtubule-based anterograde translocator for membranous organelles.
Tractability: Small molecule: a structure with a bound ligand is known; it has a high-quality binding pocket. PROTAC: ubiquitination databases record sites on it.
Target class: Other cytosolic protein
Gene: Protein-coding gene on chromosome 2 (25,926,589 to 25,982,761, reverse strand). Ensembl gene ENSG00000084731.
Subcellular location: Cytoplasm, cytoskeleton
Pathways (Reactome):
Hemostasis: Kinesins
Immune System: MHC class II antigen presentation
Organelle biogenesis and maintenance: Intraflagellar transport
Vesicle-mediated transport: COPI-dependent Golgi-to-ER retrograde traffic
Gene Ontology:
Molecular function: protein binding; cytoskeletal motor activity; ATP binding; microtubule binding; microtubule motor activity
Biological process: microtubule-based movement
Cellular component: ciliary tip; cilium; cytosol; kinesin complex; cytoplasm; cytoskeleton
Genetic constraint (gnomAD): Loss-of-function variants: 10 observed, 63.77 expected, observed/expected ratio (o/e) 0.16, 90% interval 0.096 to 0.27. The upper end of that interval is the gene's LOEUF score, 0.27, which puts it in group 1 of 6, group 1 being the genes least tolerant of losing a copy. Missense variants: 766 observed, 1,083.7 expected, observed/expected ratio (o/e) 0.71, 90% interval 0.67 to 0.75. Synonymous variants: 385 observed, 439.98 expected, observed/expected ratio (o/e) 0.88, 90% interval 0.8 to 0.95.
Homologues: Orthologues: chimpanzee KIF3C (99% identical), macaque KIF3C (99% identical), dog KIF3C (97% identical), guinea pig KIF3C (97% identical), pig KIF3C (96% identical), rat Kif3c (96% identical), rabbit KIF3C (95% identical), mouse Kif3c (95% identical), tropical clawed frog kif3c (76% identical), zebrafish kif3ca (68% identical), zebrafish kif3cb (58% identical), Caenorhabditis elegans klp-11 (44% identical), and 1 more. Paralogues in human: KIF3B (61% identical), KIF3A (40% identical), KIF17 (38% identical), KIF13B (28% identical), KIF1A (28% identical), KIF1B (28% identical), KIF13A (26% identical), KIF16B (26% identical), KIF11 (25% identical), KIF21B (25% identical), KIF1C (25% identical), KIF18A (25% identical), and 29 more.
Diseases named in the same sentence as KIF3C in open-access papers:
KIF3C is named in the same sentence as 23 diseases in open-access papers, as found by Europe PMC text mining. Sharing a sentence is not in itself a finding about the gene and the disease. The quoted sentences say what the papers report.
breast carcinoma (10 papers, 2016 to 2024). "KIF3C is overexpressed in breast cancer tissues, and such high KIF3C expression is also associated with tumor recurrence and lymph node metastasis." (PMID 33150178, 2020). "Similar results were also previously reported on the association between taxane resistance in basal-like breast cancer and kinesins, including KIF3C, KIF5A and KIF12." (PMID 27128470, 2016). "Furthermore, KIF3C, identified at 2p23.3, is a gene which regulates microtubule dynamics and has been previously implicated in breast cancer." (PMID 31429796, 2019). "KIF3C is an oncogene, and a previous study demonstrated that KIF3C overexpression leads to docetaxel resistance in breast cancer." (PMID 38439082, 2024). "Conversely, the suppression of KIF3C expression has been observed to hinder both tumor progression and metastasis in breast cancer, primarily through the inhibition of the TGF-β signaling pathway." (PMID 38552217, 2024). "Specifically, the up-regulation of KIF3C is accompanied by docetaxel resistance of breast cancer cells." (PMID 34193018, 2021). "In the tumor diseases, accumulated researches indicated that KIF3C exerted as an oncogene involving in glioma, breast cancer progress by activating PI3K/AKT/mTOR and TGF-β signaling pathway." (PMID 34537760, 2021). "Our results were consistent with those of a previous study in breast cancer cells, indicating the potential clinical value of KIF3C in glioma." (PMID 33150178, 2020). "The downregulation of KIF3C expression inhibits tumor growth and metastasis in breast cancer by inhibiting TGF-β signaling." (PMID 33150178, 2020). "KIF3C is found to be highly expressed in breast cancer, KIF3C and SHANK2 are both related to axons transmitting neural signals, and poor prognosis of tumor, but its role in melanoma remains to be further studied." (PMID 32547879, 2020). "KIF3C is reported to express highly in breast cancer and promote tumor progression." (PMID 34537760, 2021). "In our investigation, we found that the role of KIF3C in prostate cancer, non-small cell lung cancer (NSCLC), and breast cancer aligns with its function in gastric cancer." (PMID 38552217, 2024).
prostate carcinoma (7 papers, 2017 to 2024). A carcinoma that arises from epithelial cells of the prostate gland. "We find that five of these genes (IRF2BP2, EDARADD, GPI, HMOX1, KIF3C) were over-expressed in patient samples, and the overexpression was significantly associated with prostate cancer relapse (the onset of metastatic disease) as individual and as a group." (PMID 30478344, 2018). "For instance, KIF3C demonstrates increased expression in prostate cancer, where it has been revealed to enhance the development of prostate cancer." (PMID 38552217, 2024). "In our study, we found that the KIF3C level is increased in prostate cancer tissues, and down-regulation of KIF3C can inhibit the proliferation and invasion of prostate cancer cells." (PMID 34537760, 2021). "Our experiments have confirmed that KIF3C is highly expressed in prostate cancer tissues and cell lines." (PMID 34537760, 2021). "The immunohistochemistry results showed that the expression of KIF3C was higher in prostate cancer tissues than in the adjacent tissues." (PMID 34537760, 2021). "KIF3C was overexpressed in prostate cancer, promoting its growth migration and invasion was induced by miR-320d/METTL3 in an m6A dependent process." (PMID 34537760, 2021). "In conclusion, KIF3C was overexpressed in the prostate cancer and exerted as an oncogene involving in promoting proliferation and metastasis, which was regulated by METTL3 in m6A modification dependence." (PMID 34537760, 2021). "The KIF3C expression in prostate cancer cell lines was detected by q-RT-PCR and western blotting, the results indicated that KIF3C was overexpressed in the prostate cell lines." (PMID 34537760, 2021). "Moreover, miR-320d has been evidenced to target METTL3, thus affecting KIF3C expression through changing m6A modification on KIF3C mRNA in prostate cancer cells." (PMID 36614216, 2023). "KIF3C, a newly discovered prostate cancer molecule in our study, also exists in other cancers." (PMID 34537760, 2021). "Similarly, we found that KIF3C is highly expressed in prostate cancer and is closely related to the prognosis of the disease as well." (PMID 34537760, 2021). "The correlation of KIF3C expression with the prostate cancer clinical features." (PMID 34537760, 2021). "Therefore, we used bioinformation based predictions to find the presence of m6A modification in KIF3C and hypothesized that KIF3C overexpression in prostate cancer is mediated by its m6A modification." (PMID 34537760, 2021). "Furthermore, miR-320d can inhibit KIF3C expression by targeting METTL3 to inhibit the growth and invasion of prostate cancer." (PMID 36591520, 2022). "Hence, our study aimed to explore the role of the regulatory mechanism of KIF3C, METTL3, and miR-320d in developing prostate cancer." (PMID 34537760, 2021). "It is confirmed that kinesin protein is associated with a variety of malignancies, and the KIF3 family is related to cancer, but the relationship between KIF3C and prostate cancer is not clear." (PMID 34537760, 2021).
glioma (6 papers, 2012 to 2025). A benign or malignant brain and spinal cord tumor that arises from glial cells (astrocytes, oligodendrocytes, ependymal cells). "Two recently published studies report that, in glioma, up-regulation of KIF3C is associated with patients’ unfavorable prognosis; functionally, KIF3C can regulate the PI3K/AKT/mTOR signal pathway to inhibit glioma cell growth." (PMID 34193018, 2021). "Surprisingly, in glioma, we observed an opposing effect of KIF3C compared to its role in gastric cancer." (PMID 38552217, 2024). "The level of KIF3C expression was identified by western blot analysis in U87 and U251 glioma cell lines." (PMID 33150178, 2020). "In this study, we conducted an in vitro study to investigate the function and mechanism of KIF3C in the process of proliferation, migration, invasion, and apoptosis in glioma cells." (PMID 33150178, 2020). "Glioma cells had a higher invasive ability after increasing KIF3C expression, while the shRNA-KIF3C group had a less invasive ability in the two cell lines." (PMID 33150178, 2020). "We first found that overexpression of KIF3C promoted cell proliferation, migration, and invasion and suppressed cell apoptosis, while silencing of KIF3C had the opposite effects on both glioma cell lines." (PMID 33150178, 2020). "Our results indicate that KIF3C promotes proliferation, migration, and invasion and inhibits apoptosis in glioma cells, possibly by activating the PI3K/AKT pathway in vitro." (PMID 33150178, 2020). "We found that overexpression of KIF3C in glioma cell lines promoted cell proliferation, migration, and invasion and suppressed apoptosis, while silencing of KIF3C reversed these effects." (PMID 33150178, 2020). "In this study, a variety of tests including CCK-8, migration, invasion, and flow cytometry assays, and western blot were conducted to explore the role of KIF3C in glioma cell lines (U87 and U251)." (PMID 33150178, 2020). "Further study will explore the expression and function of KIF3C in high- and low-grade glioma tissues and in vivo." (PMID 33150178, 2020). "Western blotting results showed that in the glioma cell lines, the KIF3C downregulation group exhibited reduced levels of PI3K and phosphorylated AKT (Ser473)." (PMID 33150178, 2020). "In this study, we conducted comprehensive research in vitro to explore the function of KIF3C in glioma." (PMID 33150178, 2020). "We first confirm that overexpression of KIF3C promotes proliferation, migration, and invasion and inhibits apoptosis in glioma cells." (PMID 33150178, 2020). "We further explored the mechanisms of KIF3C on proliferation, migration, and invasion in glioma cells." (PMID 33150178, 2020). "For example, KIF3C may promote the proliferation, migration and invasion of glioma cells by activating the PI3K/AKT/mTOR pathway in vitro, inhibit the apoptosis of cancer cells, and prolong survival time." (PMID 40964093, 2025). "Another study shows that KIF3C expression in the low-grade glioma tissue is higher in comparison to the high-grade glioma tissue, and patients with high KIF3C expression have a longer survival time; functionally, KIF3C inhibits glioma cells’ growth through modulating the PI3K/Akt/mTOR pathway." (PMID 34193018, 2021). "As for the lack of relevant research, we hypothesize that the expression level of KIF3C in different-grade gliomas (grades I to IV) may vary because of differentiation and dedifferentiation." (PMID 33150178, 2020). "KIF3C might act as a potential biomarker or therapeutic target for further basic research or clinical management of glioma." (PMID 33150178, 2020). "We then treated U87 and U251 cells with the AKT inhibitor MK-2206 (Selleck Chemicals, USA) to investigate whether AKT phosphorylation could mediate KIF3C-induced glioma progression." (PMID 33150178, 2020).
glioma (continued). "However, in the CNS, the KIF3C peptide can efficiently induce glioma-reactive cytotoxic T lymphocytes (CTLs) from patients, indicating an effective peptide-based immunotherapy for glioma patients." (PMID 33150178, 2020). "Since KIF3C is expressed in the CNS, we investigate whether KIF3C has a potential role in glioma." (PMID 33150178, 2020). "However, the exact function and possible mechanism of the motor protein KIF3C in glioma remain unclear." (PMID 33150178, 2020). "KIF3C has also been identified as a factor that can impede glioma growth by modulating the PI3K/AKT/mTOR pathway, thereby extending the survival of glioma patients, and offering a prospective target for glioma treatment." (PMID 38552217, 2024). "Treatment of glioma cells with an AKT inhibitor suppressed the expression levels of N-cadherin and p-AKT in KIF3C-overexpressing cells." (PMID 33150178, 2020). "Altogether, our data suggest that KIF3C is probably involved in the PI3K/AKT pathway and can induce EMT in glioma cell lines." (PMID 33150178, 2020). "Therefore, we investigated whether KIF3C was involved in the PI3K/AKT pathway in glioma cells." (PMID 33150178, 2020). "In addition, treatment of glioma cells with an AKT inhibitor suppressed the expression levels of N-cadherin and p-AKT in KIF3C-overexpressing cells." (PMID 33150178, 2020). "Taken together, these results indicate that KIF3C may be involved in the PI3K/AKT pathway and induce EMT in glioma cells." (PMID 33150178, 2020). "In the majority of glioma cell lines, 3 genes were overexpressed: KIF1C, KIF3C, and KIF21B." (PMID 23320178, 2012).
gastric cancer (1 paper, 2024). A primary or metastatic malignant neoplasm involving the stomach. "In an effort to delve deeper into the functional network and pathogenic mechanisms associated with KIF3C in GC, we implemented KIF3C gene expression knockdown in gastric cancer cell lines characterized by high KIF3C expression." (PMID 38552217, 2024). "Nevertheless, the precise role and associated mechanisms of KIF3C in the initiation and development of gastric cancer remain incompletely understood." (PMID 38552217, 2024). "Following a comprehensive examination of the gene expression profiles in the gastric cancer cohort from the TCGA database, we found a total of 2087 genes that exhibited differential expression between the high and low KIF3C expression groups." (PMID 38552217, 2024). "We firmly believe that, with the refinement of related basic and clinical experiments, KIF3C holds the potential to emerge as a novel therapeutic target for gastric cancer, offering promise for improved outcomes among gastric cancer patients." (PMID 38552217, 2024). "All these findings indicate the potential involvement of KIF3C in the PI3K/AKT pathway in the context of gastric cancer." (PMID 38552217, 2024). "Employing a multidimensional analysis, we assessed the independent prognostic value of KIF3C in gastric cancer (GC)." (PMID 38552217, 2024). "In summary, our research findings reveal a significant relationship between KIF3C and the prognosis of gastric cancer patients, as well as the biology of cancer cells." (PMID 38552217, 2024). "To acquire insights into the influence of KIF3C on the advancement of gastric cancer, we employed a method involving the suppression of KIF3C expression in gastric cancer cells by transfecting them with si-KIF3C." (PMID 38552217, 2024). "Our research has demonstrated a notable connection between elevated KIF3C expression in gastric cancer (GC) and unfavorable clinicopathological features, as well as poorer patient survival." (PMID 38552217, 2024). "Drug sensitivity unveiled a positive relationship between KIF3C in gastric cancer and the IC50 values of the majority of identified anti-cancer drugs." (PMID 38552217, 2024). "Subsequent survival analysis revealed that an elevated KIF3C is related to an unfavorable prognosis in gastric cancer." (PMID 38552217, 2024). "However, there is presently a scarcity of research pertaining to the potential molecular mechanisms and gene functions of KIF3C in gastric cancer." (PMID 38552217, 2024). "Moreover, this heightened KIF3C expression was corroborated in gastric cancer cell lines and datasets." (PMID 38552217, 2024). "In addition, we conducted in vitro experiments to substantiate the role of KIF3C in gastric cancer (GC)." (PMID 38552217, 2024). "This suggests that, in contrast to other tumor types, KIF3C may exert a more substantial influence on the initiation and development of gastric cancer." (PMID 38552217, 2024). "Additionally, KIF3C knockdown reduced the proliferation, migration, and invasion capabilities, increased apoptosis, and led to alterations in the cell cycle of gastric cancer cells." (PMID 38552217, 2024). "Moreover, KIF3C demonstrated varying relationships with the infiltration of various distinct immune cell types in gastric cancer." (PMID 38552217, 2024). "Our analysis revealed that KIF3C exhibited upregulation in gastric cancer (GC) samples when compared to normal gastric cell lines, as demonstrated by qPCR analysis." (PMID 38552217, 2024).
gingival fibromatosis (1 paper, 2023). "Moreover, in our study, we found that heterozygous or homozygous mice with Kif3c mutation alone did not exhibit symptoms of gingival fibromatosis." (PMID 37752101, 2023). "Thus, we speculate that the high expression of this gene resulting from this mutation may affect the differentiation of gingival fibroblasts and promote the development of disease; however, mutation of KIF3C alone is not sufficient to cause the development of gingival fibromatosis." (PMID 37752101, 2023).
gingival tumor (1 paper, 2023). "Furthermore, we observed that ZNF513 and KIF3C expression was significantly increased in patient gingival tumor tissue and primary gingival fibroblasts." (PMID 37752101, 2023).
lung adenocarcinoma (1 paper, 2021). A carcinoma that arises from the lung and is characterized by the presence of malignant glandular epithelial cells. "The data showed that KIF3C expression level in NSCLC tissues (lung adenocarcinoma: LUAD; lung squamous carcinoma: LUSC) was markedly higher compared with normal tissues." (PMID 34193018, 2021).
Sepsis (1 paper, 2024). Sepsis is defined as life-threatening organ dysfunction caused by a dysregulated host response to infection. "It was noted that several genes with DRE were previously reported or implicated to play a role in sepsis or SAE, such as superoxide dismutase 2 (SOD2), Miat, peptidylarginine deiminase 2 (Padi2), Shank1, transcription factor 4 (Tcf4) and kinesin family member 3 (Kif3c)." (PMID 39135964, 2024).
stomach adenocarcinoma (1 paper, 2024). "Notably, in patients with stomach adenocarcinoma (STAD) who had higher KIF3C expression levels, there was increased sensitivity to specific drugs, including Axitinib, Bexarotene, Dasatinib, Doxorubicin, Elesclomol, Embelin, Etoposide, Imatinib, Nilotinib, Pazopanib, Shikonin, and Vorinostat." (PMID 38552217, 2024).
thyroid cancer (1 paper, 2024). "As for thyroid cancer, there haven’t been reports on the impact of KIF3C that we’ve come across." (PMID 38552217, 2024).